CRP (C-reactive protein)
Diseases named in the same sentence as CRP in open-access papers (continued):
Sharing a sentence is not in itself a finding about the gene and the disease.
bacterial infection (continued). "PCT, with its higher specificity for bacterial infections, demonstrates superior diagnostic accuracy compared to CRP." (PMID 39469363, 2024). "Both total white cell count and C reactive protein at baseline were independently associated with documented bacterial infections in our cohort." (PMID 38243171, 2024). "HBP, PCT, and CRP are commonly used indicators for predicting infectious diseases in clinical practice and have high diagnostic value in various bacterial infections." (PMID 39611102, 2024). "It is important to note that CRP has consistently demonstrated superior diagnostic performance in the context of bacterial infections." (PMID 39296886, 2024). "In the context of our study, we also evaluated the diagnostic performance of NLR, PLR, and CRP in predicting bacterial infections using the Receiver Operating Characteristic (ROC) curve areas (AUC)." (PMID 39296886, 2024). "Both PCT and CRP showed moderate diagnostic efficiency in differentiating between GP and GN bacterial infections." (PMID 38172766, 2024). "For each additional unit (1%) increase in neutrophils, the risk of bacterial infection in newborns increased by 6.6%, while for each additional unit (1 mg/L) increase in CRP, the risk of bacterial infection in newborns increased by 9.4%." (PMID 37679686, 2023). "As a result, it was suggested that CRP levels above 50 mg/dL are typically caused by a high rate of bacterial infection and have been used as a prognostic indicator for both acute and chronic cases of hepatitis C, dengue fever, and malaria." (PMID 37860004, 2023). "The specificity and diagnostic accuracy of CRP were lower than that of procalcitonin also in differentiating bacterial infections from disease flare-ups in patients with systemic rheumatic diseases in a meta-analysis of eight studies, including 668 patients." (PMID 37016028, 2023). "Of the different categorical variables tested, only c-reactive protein (CRP) (≥42.3 mg/dL), neutrophil count (≥10.2), and age (odds ratio = 1.185, p = 0.013 and 95%CI = 1.037–1.354) had significant diagnostic capability for bacterial disease prediction." (PMID 37892652, 2023). "The highest levels of CRP are found in serum, and a bacterial infection can cause its values to increase up to 1.000-fold." (PMID 37627653, 2023). "Since then, CRP has been linked to bacterial infections generally, as well as other etiologies of inflammation." (PMID 37275364, 2023). "CRP is well known as a biomarker associated with exacerbations mainly caused by bacterial infections, and this association has good sensitivity and specificity." (PMID 37109072, 2023). "In many studies, CRP has been implicated as an acute phase reactant associated with disease severity in pediatric bacterial infections." (PMID 37102779, 2023). "We proposed a diagnostic algorithm, which added WBC counts and CRP into the decision making, in order to identify bacterial infections in patients with a nCD64 AU MFI lower than 9.4." (PMID 36915043, 2023). "CRP is also considered an acute-phase reactant associated with disease severity in children with bacterial infection." (PMID 37383272, 2023). "At first, doctors felt tempted to prescribe antibiotics based on elevated markers of inflammation, reminiscent from previous times when a high CRP value was frequently associated in clinical practice with a bacterial infection." (PMID 35683579, 2022). "It is important to note that bacterial infections are associated with an exacerbation of MS symptoms, and bacterial infection can promote an increase in levels of CRP." (PMID 35335126, 2022). "We compared peripheral blood conventional indicators (WBC, NLR, PCT, CRP) and T lymphocyte subsets among groups to evaluate indicators’ diagnostic power in bacterial infections." (PMID 36443747, 2022). "During inflammation, the plasma levels of CRP deviate by at least 25%, causing an increase in the circulating levels of CRP by up to 1,000-fold due to bacterial infections." (PMID 35915684, 2022).
bacterial infection (continued). "Researchers have examined CRP as a diagnostic tool in screening for inflammation and detecting bacterial infections." (PMID 35968461, 2022). "Crackles-only were also more commonly detected on conventional auscultation among 81 cases with CRP ≥40 mg/L (51.9% vs 17.3%, p<0.001), a marker typically associated with bacterial infection." (PMID 35577452, 2022). "A subsequent bacterial infection was diagnosed in patients displaying elevated levels of PCT or CRP or an isolated pathogenic bacterial species in blood, alveolar lavage fluid, air intubation, or sputum samples." (PMID 35579467, 2022). "Sub-analysis of the PERCH trial, published in 2017, similarly found that elevated CRP was associated with bacterial infection, highlighting it as a potentially useful biomarker to identify children with bacterial infection." (PMID 36370376, 2022). "For reference, in a study including 147 dogs with CRP concentrations greater than 100 ug/mL, 86/147 dogs had an associated inflammation, but only 33/147 (22%) of them had a confirmed bacterial infection and 11 dogs had a viral infection." (PMID 36290272, 2022). "Bacterial infection triggers the hepatic metabolic pathway to produce acute-phase proteins, causing a rapid increase (hours) in CRP and PCT serum levels." (PMID 35208760, 2022). "Compared to white cell count and procalcitonin level, the C-reactive protein level had the best diagnostic accuracy for documented bacterial infections (area under the curve, AUC of 0.822)." (PMID 35203787, 2022). "PCT has higher specificity for bacterial infections, when compared to CRP, but its diagnostic accuracy can be affected by prior exposure to antibiotics." (PMID 36195852, 2022). "While we observed no direct correlation between sIC reactivity and either PCT (indicative of bacterial infection) or IL-6 levels sIC levels were directly associated with CRP and LDH, both undisputed correlates of severe COVID-1911." (PMID 36163132, 2022). "Increased CRP and ferritin levels were also associated with secondary bacterial infection and poor clinical outcomes." (PMID 33628256, 2021). "Although a commonly used marker in critical illness, CRP lacks specificity for bacterial infection and is seen to rise in most other causes of inflammation." (PMID 34720754, 2021). "Levels of C-reactive protein (CRP) are often used as a diagnostic marker for bacterial infection commonly used in practice." (PMID 34198509, 2021). "High levels of white blood cells (WBC), absolute neutrophils count (ANC), and C-reactive protein (CRP) are usually considered associated with bacterial disease." (PMID 34746044, 2021). "The kinetics of the PCT are between that of IL-6 and that of CRP, mainly associated with bacterial infection." (PMID 33708198, 2021). "In particular, the combination of CRP and IgM has been reported to be a more accurate diagnostic marker for the detection of neonatal bacterial infections." (PMID 33081061, 2020). "Good diagnostic performance of CRP in identifying bacterial infections was observed, but generalisability was limited due to demographic, clinical and diagnostic heterogeneity of these studies." (PMID 32437937, 2020). "C-reactive protein (CRP) was considered as one of the best markers for measuring inflammation caused by bacterial infection or tissue damage, which was produced by stimulation of interleukin-1 (IL-1) and interleukin-6 (IL-6) in liver." (PMID 32246038, 2020). "In a multivariate analysis of clinical and laboratory parameters in febrile ED patients, elevated serum CRP and history of rigours were significantly associated with bacterial infection." (PMID 32690014, 2020). "No factors in postoperative blood data showed associations with complications, including CRP, white blood cells, and neutrophils, which were considered as markers of bacterial infection." (PMID 31429742, 2019).
bacterial infection (continued). "In consistence with the findings of earlier records, the current study has indicated that the diagnostic specificity of PCT in detecting bacterial infection is superior to CRP in GPP patients." (PMID 31777354, 2019). "A substantive example is presented using C reactive protein as a diagnostic marker for bacterial infection in the older adult population." (PMID 29367318, 2018). "Recently, several studies have found an association between CRP and severity of bacterial infections." (PMID 29312224, 2017). "Results show that CRP levels were positively correlated with positive cultures where increase in CRP levels was associated with increased probability of bacterial infection in the blood." (PMID 28451028, 2017). "CRP is an acute phase protein that has been linked to the presence and severity of bacterial infection in numerous studies during the past 2 decades." (PMID 28991170, 2017). "A study in Malawian children found significantly higher CRP levels in bacterial infections compared to patients with viral causes (median 185.4 vs. 18.3 mg/l, p<0.001)." (PMID 27486746, 2016). "In contrast, bacterial infections are commonly associated with an extensive release of IL-1β, thereby stimulating the hepatocytic CRP secretion through the induction of IL-6." (PMID 27977798, 2016). "Recently, clinical studies have focused on PCT as a biomarker of bacterial infections, showing better diagnostic properties than commonly used markers such as CRP." (PMID 27048405, 2016). "Bacterial infections usually cause neutrophil activation, thus, in theory a neutrophil activation marker should be more specific for bacterial infections than e.g. CRP." (PMID 26213499, 2015). "CRP is an acute phase reactant and has been used as diagnostic marker for serious bacterial infection in hospitalized febrile infants." (PMID 25909192, 2015). "So far, the association between CRP and bacterial infections was only evaluated in the hospitalized children or at the emergency department and predominantly in younger children below three years of age." (PMID 24764729, 2014). "More recently, several authors have reported the quantitative evaluation of CRP as a diagnostic marker of bacterial infections, sensitivity and specificity ranging from 57% to 100% and from 50% to 100%, respectively." (PMID 24764729, 2014). "An elevated CRP can indicate either a concomitant bacterial infection or active inflammatory process associated with PG." (PMID 25374597, 2014). "In conclusion, neutrophil and IG levels together with CRP constitute a rapid and cheap diagnostic tool with moderate diagnostic value in children with bacterial infections." (PMID 24764729, 2014). "The aim of this study was to evaluate the usefulness of CRP and leukocyte populations as early diagnostic markers of bacterial infections in febrile outpatient children." (PMID 24764729, 2014). "Other studies have evaluated the effect of CRP as a predictor of bacteraemia and have found that CRP has limited validity as a diagnostic test for bacterial infections, because of the low positive predictive value and a poor discriminatory value." (PMID 25027551, 2014). "Limited data imply that increased PCT levels (> 0.5 ng/mL) have a greater diagnostic specificity than CRP in distinguishing bacterial infections." (PMID 24696696, 2014). "In contrast, the serum CRP level cannot be used to differentiate bacterial infections from other causes and is therefore less useful for diagnosing systemic inflammation." (PMID 23843799, 2013). "Its rapid synthesis, short half-life and rapid decline with recovery, together with an association between greater increases and serious bacterial infections, have made the CRP test popular." (PMID 22943554, 2012). "For patients with complications, the secondary bacterial infection which causes elevation in leucopenia and C-reactive protein is most likely to occur." (PMID 22022474, 2011).
bacterial infection (continued). "We conclude that there exists a statistically significant association between age and CRP in invasive bacterial infections." (PMID 18706087, 2008). "However, while CRP demonstrates high sensitivity, its limited disease specificity and frequent elevation in various viral or bacterial infections reduce its standalone diagnostic utility." (PMID 41169895, 2025). "While CRP alone shows relatively high diagnostic utility, its limited disease specificity and overlap with other inflammatory febrile conditions—including viral or bacterial infections—reduce its reliability as a standalone diagnostic marker." (PMID 41169895, 2025). "This might be attributed to the increased IL-6 production during bacterial infection, which caused an upsurge in hepatic CRP synthesis." (PMID 39946377, 2025). "However, a meta-analysis of the performance of PCT to that of CRP for serious bacterial infections in young infants suggests that they hold similar diagnostic accuracy metrics." (PMID 41149760, 2025). "Given that impaired iron absorption plays a protective role during bacterial infections, the underlying causes of CRP elevation could significantly impact the extent of iron absorption impairment." (PMID 40148488, 2025). "CRP (OR = 1.014, 95% CI: 1.002–1.026, p = 0.017) and cortisol (OR = 1.007, 95% CI: 1.002–1.012, p = 0.003) were found to have an independent association with bacterial infection in DKA patients." (PMID 39946377, 2025). "(p.5) Encouraging the use of diagnostic tests designed to distinguish viral from bacterial infections, such as CRP testing, was thought to enable prescribers more accurately to decide on an antibiotic prescription (or none), and thus decrease inappropriate prescribing." (PMID 40887118, 2025). "Limited evidence suggests that serum C-reactive protein > 60 mg/L and procalcitonin ≥ 2 μg/L can be used as diagnostic markers to identify bacterial infections in children with LRTIs and may provide guidance for the administration of antibiotics." (PMID 38064012, 2024). "CRP has good diagnostic value for local bacterial infections." (PMID 39411281, 2024). "Indeed, during pregnancy and labour, CRP is mainly used to identify underlying bacterial infection and/or to monitor prolonged labour." (PMID 38937587, 2024). "Severe viral or bacterial infections cause inflammation with increment of C-reactive protein (CRP) and neopterin and oxidative stress with increased production of reactive oxygen species (ROS) and reactive nitrogen species (RNS) and subsequent increment of NOx levels." (PMID 38891025, 2024). "Even though bacterial infections are clearly associated with higher concentrations of CRP, its utility for the detection of microbial etiology has been proved to be limited by poor specificity when lower cutoffs are used and on the other side by low sensitivity when using higher cutoffs." (PMID 38509997, 2024). "However, even if combined with bacterial infections (after adjusting for use of antibiotics), CRP and PCT were significantly associated with the prevalence of DKA or HHS." (PMID 38455656, 2024). "Bacterial infection, inflammation, and necrosis cause raised C-reactive protein (CRP)." (PMID 37213962, 2023). "Bacterial infections, which may contribute to elevated CRP concentration, are a potential cause of PAD and CAD." (PMID 37664733, 2023). "It is widely acknowledged that certain viruses, such as HAdV and HBoV, are associated with high fever and a significant increase in C-reactive protein levels, which may mimic bacterial infections." (PMID 38133281, 2023). "This suggests that CRP, at a cut-off of 32.6mg/L, might be the best available diagnostic test for excluding bacterial infection in febrile children in lower-resource settings." (PMID 37478118, 2023). "For example, infectious gastroenteritis or severe viral or bacterial infections may cause CRP levels to be elevated, masking CD-associated CRP elevations." (PMID 37576142, 2023).
bacterial infection (continued). "Reducing the intensity of the inflammatory response associated with bacterial infection, in particular, reducing the level of CRP, may be one of the effects of the bacteriophage application." (PMID 36560618, 2022). "Furthermore, serum zinc levels were negatively associated with biomarkers of inflammation and bacterial infection including interleukin‐6, erythrocyte sedimentation rate, CRP, and procalcitonin." (PMID 36245940, 2022). "Genetic deficiencies of key mediators of the innate immune response, autosomal recessive IRAK4, and X-linked recessive IKBKG (encoding for NEMO) deficiencies, underlie pyogenic bacterial infection with impaired interleukin-6 (IL-6) production and C-reactive protein (CRP) production." (PMID 32067109, 2020). "Many studies have proposed that high CRP concentration may be associated with severe bacterial infection in febrile infants and children." (PMID 32429293, 2020). "Second, we aimed to determine which biomarkers among a cut-off value of the 95th percentile in the serum PCT reference curve, WBC count, and CRP and IgM levels, alone or in combination, have the highest diagnostic accuracy for detecting early-onset neonatal bacterial infections." (PMID 33081061, 2020). "As the half-life of CRP is about 19 h, which is long enough for the steady time course, its repeated measurement has been generally used despite considerably varying data regarding its diagnostic accuracy as a marker in predicting bacterial infections." (PMID 32326479, 2020). "This suggests that sputum IL-1β or serum CRP concentrations could be used as biomarkers for identifying patients with COPD whose exacerbations are associated with bacterial infection and who may benefit from anti–IL-1 treatment approaches." (PMID 28793896, 2017). "C-reactive protein (CRP) is an acute-phase protein, which increases with bacterial infections and could therefore be of diagnostic value." (PMID 26937636, 2016). "CRP is increased during bacterial infections which could be the cause of the exacerbations in the patients with COPD." (PMID 27013031, 2016). "However, the agreement between POC and laboratory methods for both WBC and CRP were considered sufficient for the purposes of identifying children at risk of severe bacterial infection." (PMID 26034987, 2015). "Although some studies have demonstrated that at least 2 CRP levels, both ≤ 10 mg/L and obtained 24 h apart, are needed to identify infants unlikely to be infected, the high cut-off value associated with bacterial infection in neonates is still uncertain." (PMID 26259626, 2015). "However, a multivariate model showed that CRP was the only independent variable for the association between viral and bacterial infections." (PMID 24764729, 2014). "Four studies examined attitudes towards C-reactive protein (CRP) POCTs or hypothetical tests which could similarly distinguish between viral and bacterial infections: we refer to these as diagnostic." (PMID 23945264, 2013). "This may be due to an increase in CRP in response to inflammation caused by bacterial infection or other conditions, and their role is to bind to phosphocholine on microbes and clear necrotic and apoptotic cells." (PMID 24013136, 2013). "In adult intensive care, PCT may have advantages over CRP in differentiating bacterial infection from other causes of inflammation." (PMID 23272177, 2012). "The implementation of CRP POCTs, guided by evidence-based recommendations, aligns with national antimicrobial stewardship initiatives, with a focus on integrating diagnostic tools like POCTs into clinical assessment pathways to help differentiate viral from bacterial infections." (PMID 40436444, 2025). "In addition, it is possible that targeting CRP use to children for which risk of bacterial infection is determined to be low or intermediate after initial clinical assessment, as opposed to all comers with ARI, may maximize its cost-effectiveness." (PMID 39159269, 2024).